TLR4 (toll like receptor 4)
Diseases named in the same sentence as TLR4 in open-access papers (continued):
Sharing a sentence is not in itself a finding about the gene and the disease.
memory impairment (continued). "Carvacrol inhibits memory impairment and inflammation in LPS-treated rats, the carvacrol showed anti-inflammatory effects mediated by BDNF and TLR4 regulation." (PMID 36557252, 2022). "For instance, memory impairment was reduced after ICV injection of Aβ oligomers by pre-treatment with TLR2 and TLR4 agonists." (PMID 31507408, 2019). "Therapeutic blockade of TLR4 signaling using the cyanobacterial product CyP injected intracerebroventricularly (ICV) was able to reduce memory impairment and glial cell activation induced by ICV administration of Aβ oligomers." (PMID 31507408, 2019). "Strawberry and selenium, when administered individually, significantly attenuated memory impairment, oxidative stress, neuroinflammation, and apoptosis, as evidenced by marked normalization of Nrf2/HO-1, TAC, SOD, MDA, TLR4/NF-κB/TNF-α, NLRP3/CASP-1/IL-1β, and BAX/Bcl-2 signaling." (PMID 41471381, 2025). "One study showed, injection of αSynOs in the brain ventricles of wild type mice caused memory impairment through a TLR-2 dependent mechanism, which is closely associated with activation of glial cells in the hippocampus; and contrary to AβOs, TLR-4 was not involved in memory impairment." (PMID 35885050, 2022). "While seeking further insight on the molecular mechanisms linking AβOs and microglial activation toward memory impairment, we also confirmed that TLR4 are vital, since neither memory impairment nor glial activation was observed in TLR4 null mice receiving AβOs ICV." (PMID 31333460, 2019).
glioblastoma (36 papers, 2015 to 2025). The most malignant astrocytic tumor (WHO grade IV). "In a glioblastoma model, intratumorally injected LPS caused a 50 % reduction in TLR4 deficient animals and nearly total subcutaneous tumor removal in wild-type BALB/c mice." (PMID 40727443, 2025). "LPS can activate Toll-like receptor 4 (TLR-4) signalling, which is implicated in the pathogenesis of glioblastoma multiforme." (PMID 33800707, 2021). "Interestingly, TLR-4, a protein belonging to the family of toll-like receptors that participate in the inflammatory response and the transcription factor Sp1, have been linked to the progression of glioblastoma multiforme (GBM)." (PMID 36520928, 2022). "HA stimulation also activates the TLR-4-signaling pathway, which plays a key role in the proliferation and differentiation of glioblastoma stem-like cells." (PMID 40507943, 2025). "TLR4 is commonly downregulated in glioblastoma, as toll-like receptor 4 (TLR4) signaling suppresses retinoblastoma binding protein 5 (RBB5) expression, a protein that acts as a stem cell transcription factor to promote self-renewing capacity." (PMID 35456993, 2022). "In this study, ACT001, an orphan drug currently in clinical trials for the treatment of glioblastoma, was identified as a TLR4 antagonist." (PMID 35757727, 2022). "Based on these findings, in the present report, we evaluated the contribution of α2δ-1 to the proliferation and migration processes of U87 human glioblastoma cells and its possible regulation through the activation of TLR-4 and Sp1 signaling pathway." (PMID 36520928, 2022). "In this report, we show evidence that TLR-4 activation by LPS increases the expression of the α2δ-1 subunit and promotes the proliferative and migratory potential of U87 human glioblastoma cells." (PMID 36520928, 2022). "We previously demonstrated an increased TLR4 expression in human astrocytoma, particularly glioblastoma (WHO-grade IV astrocytoma)." (PMID 33446690, 2021). "Glioblastoma cancer stem cells exhibit a lower expression of the innate immune receptor TLR4 (Toll-like receptor 4), which helps them to evade inhibitory innate immune signaling." (PMID 33302406, 2020). "The TLR-4 signaling pathway is also triggered by HA stimulation and plays an important role in glioblastoma stem-like cell proliferation and differentiation." (PMID 32957463, 2020). "During differentiation, glioblastoma stem-like cells upregulate TLR-4, release HA, and activate the TLR-4-NFκB signaling pathway." (PMID 32957463, 2020). "Despite low TLR4 expression glioblastoma stem cells express high levels of TLR2, and its stimulation by high-mobility group box 1 (HMGB1) enhanced the stemness markers of those cells." (PMID 31695691, 2019). "Using RT-PCR and immunohistochemistry, we examined the expression of TLR4 in 34 glioblastoma clinical samples." (PMID 28641579, 2017). "Immunohistochemical detection revealed that TLR4 protein is overexpressed in tissues from glioblastoma patients." (PMID 28881826, 2017). "We used immunohistochemistry to determine the expression and localization of the TLR4 protein in glioblastoma." (PMID 28641579, 2017). "In addition, the expression of TLR4 can influence the proliferation patterns in cancer stem cells and glioblastoma multiforme cells." (PMID 37822929, 2023). "However, TLR4 expression was observed to be lower in glioblastoma (GB) tumors when compared to astrocytomas, and such downregulated level of TLR4 was reported both in chemoresistant GB and in macrophages co-cultured with GB cells." (PMID 37822929, 2023). "Previous studies in human tumors have shown that Sp1 and TLR-4 participate in glioblastoma development; therefore, the overexpression of these proteins was subsequently evaluated separately in U87 glioblastoma cells to assess their role in cell proliferation and migration." (PMID 36520928, 2022).
glioblastoma (continued). "In the present study we investigated the expression of Dkk-3, claudin-5, apoptosis markers and TLR-4 receptor protein levels in in vitro studies on U-138MG, A-172, LN-18 and LN-229 human glioblastoma cell lines, and in vivo study using TLR-4 KO mice and in glioblastoma human patient’s tissues." (PMID 30680070, 2018). "Additionally, TLR ligation is related to adhesion and metastasis in human colorectal cancer cells and migration in human glioblastoma (via TLR4) and human breast cancer cells (via TLR2)." (PMID 27941651, 2016). "In another study, EGFR transactivation, which may contribute to cell migration, induced by HSP90a in U87 glioblastoma cells was inhibited with the down-regulation of TLR4, indicating that HSP90a promotes glioblastoma cells migration through the interacting with TLR4." (PMID 29029545, 2017). "In HBMECs exposed to conditioned media from glioblastoma cell lines (MCT98G or MCU87), a decrease in TLR4 staining was observed, both in the absence and presence of DBK." (PMID 40284027, 2025). "Collectively, our findings demonstrate that TMZ-induced autophagy-dependent ENO1 secretion activates two pivotal signaling axes, TLR4-mediated PI3K/Akt and SPHK1/S1P pathways, to drive glioblastoma malignancy." (PMID 41353343, 2025). "During differentiation, glioblastoma stem-like cells increase TLR-4 expression, secrete HA, and activate the TLR-4-NFκB-signaling pathway." (PMID 40507943, 2025). "targeted glioblastoma (GBM) using genetically modified Salmonella, whose lysis releases LPS that binds to TLR4 on host cells, activating the NLRP3-Caspase-1-GSDMD pathway and inducing pyroptosis." (PMID 39575419, 2024). "An analysis of metformin (MET) treatment in combination with temozolomide (TMZ) in two glioblastoma cell lines, U87MG and A172, stimulated with lipopolysaccharide (LPS), a TLR4 agonist was conducted." (PMID 36765551, 2023). "We next wanted to determine the fetuin‐A uptake in real time both in the TLR4 knockdown PC3 cells and in the LN229 glioblastoma cells in the absence and presence of CLI‐095." (PMID 33073533, 2020). "The interaction between B1R and TLR4 is disrupted by the secreted factors released by glioblastoma cells, as conditioned media from T98G and U87 reduce TLR4 staining in endothelial cells without affecting B1R expression." (PMID 40284027, 2025). "LPS, a component of the outer membrane of Gram-negative bacteria, is an agonist of the TLR4 and can modify gene expression in various cell types; it has also been identified as a potential anti-tumor agent for glioblastoma treatment." (PMID 40284027, 2025). "In addition to suppression of growth-promoting genes, GZ17-6.02 upregulated several genes shown to inhibit the growth and invasion of glioblastoma, including BDNF-AS, CREBRF, and TLR4." (PMID 35456993, 2022). "It was shown that glioblastoma stem cells have very low TLR4 expression in comparison to non-stem cells and don't respond to TLR4 stimulation, which allows them to survive despite immune signaling." (PMID 31695691, 2019). "In some data sets, COAD, esophageal carcinoma (ESCA), glioblastoma multiforme (GBM), kidney chromophobe (KICH), brain lower grade glioma (LGG), LIHC, PAAD, SKCM, STAD, and TGCT have high TLR4 gene expression." (PMID 34631699, 2021). "Interestingly, 3 was able to suppress pro-inflammatory genes, including IL-1α, IL-1β, IL-12, prostaglandin endoperoxide synthase 2 (PTGS-2), and Toll-like receptor 4 (TLR4), as well as the secretion of the pro-inflammatory cytokine IL-6 in LN-18 and T98G glioblastoma cells." (PMID 34067242, 2021). "The absence of TLR-4 inhibits the growth of glioblastoma lines." (PMID 32354122, 2020). "Previous studies reported TLR4 to be absent on glioblastoma cells, and LPS-induced antitumoral effects might depend on microglia and inflammatory cells." (PMID 28881826, 2017).
kidney damage (36 papers, 2014 to 2026). "We also showed that upregulation of some TLR members, notably TLR4, and of their endogenous ligands, such as fibrinogen, are associated to kidney damage." (PMID 35208236, 2022). "Later, the same investigators studied in the same cohort of patients, including 14 IgAN, the mRNA expression of Toll-like receptor 4 (TLR4) which would be associated with other inflammatory mediators, increased proteinuria, impaired renal function, and progression of the kidney damage." (PMID 34674036, 2021). "TLR4 on renal parenchymal cells triggers several pathways, including MAPK, which increases the production of inflammatory cytokines and causes kidney damage." (PMID 38285279, 2024). "In a rat model of rhabdomyolysis-induced acute renal damage, PTX improved the renal function markers and attenuated the pathological signs of kidney damage by dampening the TLR4/NF-κB pathway and the expression of IL-1β and TNF-α." (PMID 38931349, 2024). "Recent studies suggest that the MD2/TLR4 axis is a crucial contributor to HFD-induced nephropathy, directly stimulating NF-κB." (PMID 39765652, 2024). "Renal TLR4 expression is modest under normal conditions but increases in response to infection and/or kidney damage." (PMID 38041694, 2023). "After blocking TLR4, the secretion of dsDNA and other autoantibodies was significantly reduced, and the kidney damage was also improved." (PMID 37872565, 2023). "Recent studies demonstrated that overexpression of TLR2 and TLR4 has a crucial role in facilitating kidney damage after renal I/R." (PMID 35911649, 2022). "Prevention of inflammation-induced nephropathy in TLR4-/- transgenic mice further supports the idea that these receptors play a central role in the signaling mechanisms of inflammation." (PMID 36230117, 2022). "Our results indicate that sIgA can induce high expression of TLR4 in HRMCs, promoting cytokine production and leading to kidney damage." (PMID 32388684, 2020). "Down-regulate TLR-4 expression on monocytes surface in a mouse model of Ischemia reperfusion injury resulting in milder kidney damage." (PMID 31921213, 2019). "In conclusion, the results would suggest that both TLR2 and TLR4 have the relevance to the promotion of P. gingivalis-induced nephropathy." (PMID 29018490, 2017). "Overall, LPS nephropathy represents a suitable model to study the link between the innate immune response (TLR-4/B7-1) and the kidney and is, more in general, considered a reliable approach to study mechanisms of nephrotic syndrome." (PMID 25343479, 2014). "Consistent with our results, previous studies showed that patients with SLE have elevated monocyte number compared to controls, that monocytes from SLE patients spontaneously produce IL-6, and that LPS and TLR4 responses play a role in kidney damage in SLE." (PMID 25485543, 2014). "Secretory IgA may induce high expression of TLR4 in human renal mesangial cells and further activate downstream signalling pathways, thereby mediating kidney damage in IgAN patients." (PMID 38022571, 2023). "The present experiment corroborates these claims, and it also implies that QB may be able to inhibit the HMGB1/TLR4/MyD88 pathway, thereby reduce autoantibody production, inhibit the release of inflammatory factors, and improve kidney damage." (PMID 35571092, 2022). "Our results indicate that sIgA may induce high expression of TLR4 in HRMCs and further activate downstream signalling pathways, prompting HRMCs to secrete multiple cytokines and thereby mediating kidney damage in IgAN patients." (PMID 32388684, 2020). "The purpose of this study was to investigate whether sIgA and TLR4 interact to mediate kidney damage in IgAN patients." (PMID 32388684, 2020). "Based on our previous findings and other published work, we hypothesized that sIgA may lead to cytokine production by inducing high expression of TLR4 in HRMCs, thus promoting IgAN kidney damage." (PMID 32388684, 2020).
kidney damage (continued). "The results indicated that activation of TLR4 signaling was associated with HSP and aberrant activation of TLR4 may cause kidney damage." (PMID 24926370, 2014). "The activation of TLR-4 could result in severe inflammation and kidney damage." (PMID 35889833, 2022). "Notably, NET-derived DAMPs, including cf-DNA, perpetuate renal inflammation by activating the TLR4/NLRP3 inflammasome axis, which triggers caspase-1-dependent cytokine maturation and establishes a self-amplifying “NETs–inflammasome–tissue injury” loop, a hallmark of progressive kidney damage." (PMID 41244813, 2025). "Understanding these aspects will provide new insights into the mechanisms of renal damage in hyperuricaemia and enhance our comprehension of TLR4 and NLRP3’s roles in hyperuricaemia nephropathy." (PMID 38041694, 2023). "Given the extensive inhibitory effect of sTLR2 on nephropathy-induced vascular pathology observed here, the involvement of specific TLR2 and/or TLR4 DAMP agonists were investigated." (PMID 37849759, 2023). "Despite the wealth of information supporting the contribution of TLR4 and the NLRP3 inflammasome to the pathophysiology of hyperuricaemia nephropathy, clinical application of therapies targeting these pathways remains unachieved." (PMID 38041694, 2023). "As a specific inhibitor of TLR4, the benefit of TAK242 against histological kidney damage indicates a potential role of TLR4 in burn-induced AKI, while the effect of the NF-κB inhibitor PDTC suggests a pivotal role of NF-κB." (PMID 33758309, 2021). "TLR-4 plays a key role in the pathophysiology of AKI and can be a promising therapeutic target to alleviate kidney damage because of these pathological stimuli." (PMID 34679755, 2021). "Given the important role of TLR4 in different kinds of preclinical AKI models, the inhibition of TLR4 and its downstream effectors can serve as the novel therapeutic target for treatment of CI−AKI through preventing renal inflammation and subsequent kidney damage." (PMID 37175958, 2023). "Activation of TLR4 indirectly promotes the assembly of the NLRP3 inflammasome by regulating the nuclear factor kappa B (NF-κB) signaling pathway, thereby amplifying the inflammatory process and playing a significant pro-inflammatory role in hyperuricaemia nephropathy." (PMID 38041694, 2023). "Activation of TLR4 and the NLRP3 inflammasome promotes the maturation and release of caspase-1, along with downstream cytokines such as IL-1β and IL-18, triggering a persistent pro-inflammatory state crucial for the continued progression of hyperuricaemia nephropathy." (PMID 38041694, 2023). "And their further study investigated that TLR4 antagonist CRX-526 could reduce albuminuria and blood urea nitrogen without altering blood glucose and systolic blood pressure in diabetic mice, thus protecting diabetic mice from advanced nephropathy." (PMID 24779014, 2014). "Also, TLR4, AOC3, IRF4, and TNFAIP6 were not differentially expressed in non-drug-induced AKI models including IRI and UUO models, which was unexpected and additional evidence of the specificity of these hub genes in drug-induced kidney damage." (PMID 37063876, 2023).